EGFR (epidermal growth factor receptor)
Diseases named in the same sentence as EGFR in open-access papers (continued):
Sharing a sentence is not in itself a finding about the gene and the disease.
pancreatic cancer (continued). "Therefore, the inhibition of EGFR by erlotinib represents an efficient strategy to overcome cell resistance to AZD8055 in pancreatic cancers." (PMID 25654224, 2015). "However, there are certain front line benefits of canertinib and afatinib (irreversible TKI), which makes it a far superior agent than EGFR specific reversible TKI erlotinib in pancreatic cancer therapy." (PMID 25686822, 2015). "In addition, the Kras; Tgfbr2flox; Cre pancreatic cancer model has been used to assess the efficacy of the EGFR (epidermal growth factor receptor) inhibitor erlotinib, as well as the effect of cancer-associated fibroblast depletion." (PMID 26438692, 2015). "EGFR is a transmembrane glycoprotein that is conserved and overexpressed in pancreatic cancer." (PMID 24722501, 2014). "Targeted therapies have mostly shown disappointing results in pancreatic cancer until erlotinib, an epidermal growth factor receptor (EGFR) tyrosine kinase inhibitor, in combination with gemcitabine, became the first treatment-additive to show a very moderate, but significant survival advantage." (PMID 25337831, 2014). "Within the current translational subgroup analysis of AIO-PK0104 we thus tried to exploratively analyze if the EGFR pathway ‘downstream’ mediators pERK and pAKT could serve as biomarkers in advanced pancreatic cancer." (PMID 25164437, 2014). "Given that EGFR protein is a client of Hsp90 and is also controlled by the ubiqutination/proteasome system, we hypothesized that CHIP could be involved in the modulation of the EGFR protein level in pancreatic cancer." (PMID 24722501, 2014). "The use of EGFR-TKIs outside of lung and pancreatic cancer is uncommon." (PMID 24527088, 2014). "However, previous reports have established that patients rapidly developed resistance, which was most likely caused by a shorter EGFR intron 1 CA repeat length, the mutation of KRAS, and the amplification of c-Met in pancreatic cancer or other tumors." (PMID 24722501, 2014). "CHIP regulates EGFR levels through the Ub-Proteasome pathway in pancreatic cancer cells." (PMID 24722501, 2014). "Interaction between EFEMP1 and EGFR has also been reported in pancreatic carcinoma cells." (PMID 25594013, 2014). "Since the introduction of gemcitabine in 1996, which is currently the gold standard for the treatment of advanced pancreatic cancer, only the EGFR TKI erlotinib has gained FDA approval for the treatment of patients with metastatic pancreatic cancer in combination with gemcitabine." (PMID 23367880, 2013). "Furthermore, preincubating pancreatic cancer cells that overexpress EGFR, such as AsPC-1, with C225 significantly reduces the uptake of ACG44 nanoconjugates, while the uptake of AIG44 remains unaffected." (PMID 23483913, 2013). "Inhibition of STAT3 sensitizes pancreatic cancer cells to tumor growth inhibition and apoptosis induced by Src or EGFR inhibitors, suggesting that co-inhibition of STAT3 may increase the efficacy of targeted therapeutics." (PMID 24015205, 2013). "Moreover, recent studies showed that members of the miR-200 family by inducing EMT can regulate the sensitivity to epidermal growth factor receptor (EGFR) in bladder cancer cells and to gemcitabine in pancreatic cancer cells." (PMID 24062980, 2013). "In contrast to human keratinocytes and pancreatic cancer cells, in medulloblastoma cells we also observed a repression of canonical HH-target genes while selected EGFR target genes were synergistically induced which can potentially contribute to the formation of a tumor-promoting microenvironment." (PMID 23762360, 2013). "EGFR over-expression is reported in up to 90% of pancreatic tumors." (PMID 24340014, 2013). "Furthermore, we investigated the impact of overexpression and small molecule inhibition on Sirt1 in pancreatic cancer cell culture models including combinatorial treatment with chemotherapy and EGFR-inhibition." (PMID 24088390, 2013).
pancreatic cancer (continued). "This hypothesis is supported by the observation that EGFR signaling synergizes with K-rasG12D to promote progression of mPanINs in the LSL-Kras mouse model of pancreatic cancer." (PMID 22359542, 2012). "The epidermal growth factor receptor (EGFR), which is overexpressed in various cancers and has been investigated in relation to cancer prognosis, is known to be an important factor in pancreatic cancer progression." (PMID 22723871, 2012). "Therefore, it seems possible to have the effect of YM155 on EGFR and its downstream signaling in pancreatic cancer cells because survivin is regulated with EGFR." (PMID 22723871, 2012). "This combination will be evaluated in various cancer patients, for example in NSCLC patients containing mutations at EGFR who have progressed after treatment with EGFR inhibitors or with patients with triple negative breast, CRC, melanoma, and pancreatic cancers." (PMID 23085539, 2012). "In studies including tumour cells from colon and pancreatic cancer, we have found that different mechanisms may be involved in the interaction of pathways from GPCRs and EGFR." (PMID 22967907, 2012). "Interestingly, in xenograft models of pancreatic cancer, the combination of gemcitabine and EGFR-targeted therapy significantly inhibited the metastatic process and resulted in improved overall survival." (PMID 22134789, 2012). "In the present study, in view of these preliminary findings we examined the biological and biochemical effects of AS104 on pancreatic cancer cells notoriously resistant to gemcitabine treatment and showing aberrant expression of EGFR and HER-2 tyrosine kinases, respectively." (PMID 22134789, 2012). "Thus, Notch-1 activation plays an important role in the growth of pancreatic cancer cells, and in cell proliferation stimulated by activation of EGFR or PDGFR." (PMID 22479394, 2012). "Similarly, we recently reported that UVC irradiation induces cell growth via downregulation of epidermal growth factor receptor (EGFR) and also induces apoptosis in human pancreatic cancer cells." (PMID 22200892, 2012). "Activation of EGFR drives tumorigenesis in lung, head and neck, colorectal and pancreatic cancers." (PMID 22997576, 2012). "Hence, pancreatic cancer cells which lack HER3 become less critically dependent on EGFR signaling and, therefore, resistant to erlotinib." (PMID 23198146, 2012). "EGFR may be important in the initial growth of pancreatic tumor cells and replaced by increased expression of other growth factor receptors, like NTR1, during metastatic dissemination." (PMID 24212612, 2011). "To understand the role of multivalency on the intracellular uptake by human pancreatic cancer cell lines with variable EGFR expression, we treated AsPC-1, PANC-1 and MiaPaca-2 cells with GNP-C225 or nonspecific isotype control GNP-IgG at different antibody to GNP (Ab∶GNP) ratios." (PMID 21738572, 2011). "Proof of concept for the utility of biologics in advanced pancreas cancer occurred in 2007 when erlotinib, a small molecule inhibitor of the epidermal growth factor receptor (EGFR) pathway, in combination with gemcitabine improved survival for patients over gemcitabine alone." (PMID 22016635, 2011). "Several studies have demonstrated that EGFR is over-expressed in pancreatic cancer." (PMID 24212772, 2011). "Overall, EGFR is emerging as a candidate for further evaluation in pancreatic cancer." (PMID 24212772, 2011). "Here we provide evidence of a functional interplay between ΔNp63α and EGFR in pancreatic cancer." (PMID 22053213, 2011). "Furthermore, KRAS mutations leading to persistent activation of cellular signaling events downstream of EGFR are found in 50–95% of pancreatic cancer samples and render proliferation of tumor cells independent of EGFR." (PMID 24212612, 2011).
pancreatic cancer (continued). "The EGFR has been reported to be overexpressed in pancreatic cancer." (PMID 21722395, 2011). "Therefore, EGFR activation appears to have a pivotal role in the growth and progression of pancreatic cancer, and EGFR-mediated pathways appear to be important potential targets for new therapies for this malignancy." (PMID 21722395, 2011). "We next sought to determine whether the ability of ΔNp63α to trans-activate EGFR and 14-3-3σ promoters was unique to pancreatic cancer." (PMID 22053213, 2011). "Thus, ΔNp63α contributes to the oncogenic potential of pancreatic cancer cells, at least in part, through upregulation of EGFR and β1-integrin." (PMID 22053213, 2011). "Recently a phase three study could demonstrate the benefit of the combination of an EGFR tyrosine kinase inhibitor in combination with chemotherapy in pancreatic cancer." (PMID 16219105, 2005). "This suggests that EGFR-targeted therapy may be an effective way to treat pancreatic cancer." (PMID 39744013, 2024). "Similarly, in a study on a mouse model of pancreatic carcinoma with enhanced expression of the EGFR factor, subcutaneous administration of PA-MSHA (2.2 × 1010 cells/mL) in combination with paclitaxel (10 mg/kg, 2 times a week, for 7 weeks) led to cancerous cell apoptosis and growth inhibition." (PMID 38339275, 2024). "Interestingly, many of the pathways identified here are consistent with pathways identified in previous studies of NLRX1, including PI3K-AKT, MAPK, EGFR, NF-κB, and IL-6 signaling, and these pathways are all important to the initiation and progression of pancreatic cancer." (PMID 37342194, 2023). "Thus, the linc00976/miR-137/OTUD7B/EGFR axis may act as a potential therapeutic target for pancreatic cancer." (PMID 36694209, 2023). "A number of such cancer cell-associated receptors, including αvβ3 integrin, epidermal growth factor receptor (EGFR), vascular endothelial growth factor receptor (VEGFR) and folate receptor, have been utilized in ligand-receptor binding systems to improve targeted chemotherapy for pancreatic cancer." (PMID 37237291, 2023). "The pivotal role of the anti-EGFR Fab arm to mediate ADCC activation by BiXAbTM and the better capacity of 2MAbs with an EGFR valence to induce ADCC, compared with BiXAbTM, could be explained by the higher EGFR expression in the pancreatic cancer cell lines used in the present study." (PMID 37153618, 2023). "Furthermore, intraoperative multi-instrument fluorescence imaging with IRDye800-conjugated anti-EGFR antibody cetuximab could be used to detect pancreatic cancer with a sensitivity of 96.1%." (PMID 36145676, 2022). "Furthermore, DTLL might suppress pancreatic tumor progression by EGFR/HER2-dependent blockage of AKT/mTOR-signaling and PD-L1/PD1-mediated escape from immunosurveillance in PDAC25." (PMID 36127339, 2022). "However, knockdown of ADAM17 or treatment with anti-ADAM17 antibody MEDI3622 resulted in regression of pancreatic tumors, accompanied by down-regulated EGFR/STAT3 signaling, increased cytotoxic T cells, and decreased granulocyte-like medullary inhibitory cells in mouse models of pancreatic cancer." (PMID 36466812, 2022). "Indeed, epidermal growth factor receptor (EGFR) has been shown to mediate LRG1 activity in pancreatic cancer cells, metastatic melanoma cells, and corneal epithelium during wound repair, whereas the IL-6/STAT3 axis appears to modulate LRG1-driven neutrophil chemotaxis." (PMID 35062948, 2022). "Moreover, induction of TSPAN6 in human pancreatic cancer cells inhibits EGFR-induced expression of the EMT markers Vimentin and N-Cadherin, as well as the critical EMT transcription factor Slug, thereby linking TSPAN6 to the inhibition of EGFR-mediated EMT in human tumor cells." (PMID 35184157, 2022). "Thus, some combination of antibody conjugates engaging CEA, CDH17, TROP2, and EGFR might be successful in pancreatic cancer." (PMID 36405499, 2021).
pancreatic cancer (continued). "The Epidermal Growth Factor Receptor (EGFR) overexpression is recognized as a driver mechanism in the initiation, progression, and therapy resistance of several carcinomas such as lung, breast, and pancreatic cancers, added the interaction HOXB7/EGFR promoter region already demonstrated." (PMID 34063128, 2021). "Moreover, intraoperative multi-instrument fluorescence imaging using the anti-EGFR antibody cetuximab conjugated to IRDye800 could detect pancreatic cancer in patients with a sensitivity of 96.1%." (PMID 34681174, 2021). "Although miR-338-5p/EGFR axis has been shown to inhibit multidrug resistance and cell growth in hepatocellular carcinoma, the results of the present study indicate that miR-338-5p/EGFR axis inhibits the metastasis of pancreatic cancer partially dependent on EGF." (PMID 33937024, 2021). "Overall, 6-P might functioned as an anti-tumor drug to inhibit pancreatic cancer cell proliferation and migration in vivo and in vitro by targeting EGFR, inducing EGFR degradation through decreasing the protein stability of EGFR and enhancing the ubiquitin-mediated proteasome-dependent degradation." (PMID 34376189, 2021). "However, the mechanisms of HSF1 abnormal activation during pancreatic cancer initiation and the role of EGFR in this process remains unclear." (PMID 33422093, 2021). "The association between the overexpression of PODXL and EGFR seen in I-type periampullary tumors was not confirmed in PB-type tumors or in pancreatic cancer in Cohort 2 in the Cox regression analysis, further indicating that I-type tumors resemble and should be treated as colorectal cancer." (PMID 32587323, 2020). "Whether Ibr-7 can alter the expression of EGFR in pancreatic cancer cells is still unknown." (PMID 32963499, 2020). "Our mechanistic studies demonstrated for the first time that DTLL might suppress pancreatic tumor progress by EGFR/HER2‐dependent blockage of AKT/mTOR signaling and PDL1/PD1‐medicated escape from immunosurveillance simultaneously, unlike LDM alone as a cytotoxic agent." (PMID 30681288, 2019). "Validation of the method using clinical samples from pancreatic cancer patients with EGFR (epidermal growth factor receptor), EpCAM (epithelial cell adhesion molecule), HER2, and MUC1 (mucin-1) antibodies, indicated that the method could be used for profiling scarce cells from clinical samples." (PMID 31762967, 2019). "Second, whether the interplay between hRNase5/ANG and EGFR identified in pancreatic cancer also contributes to the signaling modulation in the pancreatic tumor microenvironment where a dense stromal matrix, including endothelial cells and fibroblasts, is a prominent histopathological hallmark." (PMID 30449278, 2018). "EGFr may generate the redistribution and expression of tight junction proteins in studies on canine renal epithelial cell lines and cell lines derived from lung and pancreatic cancers." (PMID 29508172, 2018). "Finally, considering hRNase5/ANG as a predictive biomarker in pancreatic cancer, a subset of patients with hRNase5/ANGhigh-EGFR+ population (around 30% based on plasma hRNase5/ANG estimation) may benefit from erlotinib treatment." (PMID 30449278, 2018). "EGFR‐targeting toxins in synergism to the endosomal escape mechanism of SO1861 might have an important regulatory role in the control of tumor growth in xenografts bearing human adenocarcinoma pancreatic tumors." (PMID 28755527, 2017). "Thus, EGFR has been considered a potential target for treating pancreatic cancer." (PMID 29262554, 2017). "Thus, we investigated whether CuB inhibits pancreatic cancer cell growth by modulating EGFR and its downstream signaling targets and tested whether CuB in combination with downstream EGFR signaling enhances its therapeutic efficacy." (PMID 29262554, 2017). "EGFR was not mutated in pancreatic cancer, but is overexpressed in about 90% of these tumors." (PMID 29156578, 2017).
pancreatic cancer (continued). "Therefore, blocking EGFR and its downstream signaling targets might be a rational strategy for pancreatic cancer therapy." (PMID 29262554, 2017). "Addition of the EGFR tyrosine kinase inhibitor erlotinib to gemcitabine lead to an increased OS in patients with advanced pancreatic cancer, the improvement was however modest and erlotinib is therefore rarely used for treatment of pancreatic cancer in clinical practice." (PMID 27070783, 2016). "Thus, we validated the information from the TCMSP database that EGFR might be the target of kaempferol in pancreatic cancers." (PMID 27175782, 2016). "Therefore, it is rational to label EGFR as a novel target for treatments of pancreatic cancer." (PMID 27399694, 2016). "Thus, PA-MSHA inhibits EGFR signaling and cell proliferation in pancreatic cancer cells." (PMID 27788491, 2016). "Thus, the potential mechanism by which PIM-1 affects sensitivity to the chemotherapy drug erlotinib or the expression of pancreatic cancer stem cell markers in pancreatic cancer may be by regulating the EGFR signalling pathway." (PMID 27596051, 2016). "Therefore, the prognostic ability of EGFR in pancreatic cancer is an ongoing topic of discussion." (PMID 27399694, 2016). "Thus, this study revealed that simultaneous inhibition of downstream EGFR effectors and the glutathione antioxidant pathway could mimic Nrf2 ablation and limit pancreatic cancer growth." (PMID 27754368, 2016). "Therefore, we hypothesized that EGFR-targeted adjuvant therapy combined with gemcitabine may be a promising therapeutic option in resectable pancreatic cancer patients with positive EGFR expression." (PMID 27399694, 2016). "Thus, the indirect pharmacological inhibition of MUC4 via canertinib or afatinib could result in developing pan-EGFR inhibitors as a molecular therapeutic agent against advanced pancreatic cancer." (PMID 25686822, 2015). "Therefore, inhibition of EGFR/Akt signaling pathways by purified crocetinic acid may be one reason for the significant impact in hedgehog signaling and stemness of pancreatic cancer progression." (PMID 26317547, 2015). "Additionally, the effect of canertinib could also influence the localization pattern of EGFR in pancreatic cancer cells." (PMID 25686822, 2015). "Finally, we confirmed that the inhibition of EGFR by erlotinib significantly sensitizes pancreatic cancer cells to AZD8055 in vivo and in vitro, which might suggest a novel strategy for pancreatic cancer therapy." (PMID 25654224, 2015). "Since our previous study has demonstrated that the MUC4 promoter has STAT1 binding sites and regulates MUC4 expression in pancreatic cancer cells, we investigated whether the levels of phosphorylated STAT1 could influence MUC4 in pancreatic cancer cells treated with the pan-EGFR inhibitors." (PMID 25686822, 2015). "Our results confirmed that CHIP could interact with EGFR in pancreatic cancer cells." (PMID 24722501, 2014). "Moreover, several studies have shown that EGFR inhibition has a pivotal role as an anti-tumor agent and, for this reason, several drugs targeted against EGFR are currently employed for the treatment of head and neck, colorectal, lung and pancreatic cancer." (PMID 24709958, 2014). "However, a separate study indicates that Neu1 facilitates EGFR signaling in pancreatic cancer and thus could have a tumor promoting effect." (PMID 25184537, 2014). "Overactivation of EGFR gives rise to the deregulation of this EGFR-dependent signaling network, which is involved in the development and malignancy of numerous types of human cancers including breast, head and neck, lung, bladder, colon, prostate, kidney, ovary, brain, and pancreatic cancers." (PMID 22476347, 2012). "However, EGFR TKIs are in clinical use in lung, colon, and pancreatic cancers." (PMID 22788954, 2012).